INO80E (INO80 complex subunit E)
Description:
Putative regulatory component of the chromatin remodeling INO80 complex which is involved in transcriptional regulation, DNA replication and probably DNA repair.
Synonyms: CCDC95; FLJ90652
Tractability: PROTAC: UniProt records ubiquitination sites on it; its protein half-life has been measured.
Gene: Protein-coding gene on chromosome 16 (29,995,715 to 30,005,793, forward strand). Ensembl gene ENSG00000169592.
Subcellular location: Nucleus
Subcellular location (Human Protein Atlas): Nucleoplasm; Nucleoli rim
Pathways (Reactome):
DNA Repair: DNA Damage Recognition in GG-NER
Metabolism of proteins: UCH proteinases
Gene Ontology:
Molecular function: protein binding
Biological process: chromatin remodeling; positive regulation of DNA-templated transcription; regulation of cell cycle; regulation of chromosome organization; regulation of DNA replication; regulation of DNA strand elongation
Cellular component: Ino80 complex; nucleolus; nucleoplasm; nucleus
Genetic constraint (gnomAD): Loss-of-function variants: 20 observed, 22.67 expected, observed/expected ratio (o/e) 0.88, 90% interval 0.62 to 1.28. The synonymous counts are far from expectation, so gnomAD's model fits this gene poorly and the ratio says little. Missense variants: 350 observed, 272.23 expected, observed/expected ratio (o/e) 1.29, 90% interval 1.18 to 1.4. Synonymous variants: 166 observed, 124.44 expected, observed/expected ratio (o/e) 1.33, 90% interval 1.17 to 1.52.
Homologues: Orthologues: chimpanzee INO80E (99% identical), macaque INO80E (99% identical), dog INO80E (97% identical), guinea pig INO80E (96% identical), rabbit INO80E (95% identical), rat Ino80e (94% identical), mouse Ino80e (94% identical), pig INO80E (75% identical), tropical clawed frog ino80e (55% identical), zebrafish ino80e (50% identical), Drosophila melanogaster CG18004 (31% identical).
Diseases named in the same sentence as INO80E in open-access papers:
INO80E is named in the same sentence as 6 diseases in open-access papers, as found by Europe PMC text mining. Sharing a sentence is not in itself a finding about the gene and the disease. The quoted sentences say what the papers report.
schizophrenia (7 papers, 2016 to 2025). A major psychotic disorder characterized by abnormalities in the perception or expression of reality. "In contrast, another study asserted that the association between YPEL3 and schizophrenia is due to its correlation with expression of INO80E, another possible candidate gene for BMI and risk of schizophrenia in the 16p11.2 region." (PMID 41006818, 2025). "A third transcriptomic association study using prenatal and adult brain tissues also pointed to INO80E as a risk gene for schizophrenia." (PMID 34715901, 2021). "However, when we adjusted the predicted expression of INO80E by the predicted expressions of the other two highly associated genes, INO80E remained significantly associated with schizophrenia (P = 2.3 × 10−6)." (PMID 34715901, 2021). "The only genes observed as significant in both differential expression and accessibility analysis, specifically when examining genetic risk, are INO80E and HCN2 in excitatory neurons’ layers 2/3 for schizophrenia." (PMID 40053590, 2025). "A single gene was repeatedly contributing to top pairs for bipolar disorder at 16p11.2 (INO80E, 26% of top pairs) and schizophrenia at 22q11.2 (PPIL2, 42% of top pairs)." (PMID 37267418, 2023). "The predicted expression of INO80E and TMEM219 from the discovery analyses were associated (P < 0.05) with having an ICD10 diagnosis of schizophrenia (ICD10: F20, 198 cases: INO80E P = 0.04, TMEM219 P = 0.03)." (PMID 34715901, 2021). "INO80E, the gene we identified as a driver of schizophrenia and BMI, is a chromatin remodeling gene and has rarely been considered in the context of brain-related traits." (PMID 34715901, 2021). "Two genes at 16p11.2 show predicted expression positively associated (P < 7.9 × 10−5) with schizophrenia: TMEM219 (P = 1.5 × 10−5) and INO80E (P = 5.3 × 10−10)." (PMID 34715901, 2021).
bipolar disorder (1 paper, 2023). A disorder of the brain that causes unusual shifts in mood, energy, activity levels and the ability to carry out day-to-day tasks. "We find that INO80E is a top association with bipolar disorder and ASD; this gene previously showed suggestive bipolar disorder association but did not meet experiment-wide significance criteria even with the updated models." (PMID 37267418, 2023).
cancer (2 papers, 2023 to 2024). A tumor composed of atypical neoplastic, often pleomorphic cells that invade other tissues. "Similarly, we observed RNA-specific MSI events in cancer-related genes such as MAZ (MYC Associated Zinc finger gene), INO80E (DNA-repair related gene), and RPL genes (ribosome-related genes)." (PMID 39210504, 2024). "Data from the PPI network showed that ASPHD1 is related to several proteins and genes such as KIF22, INO80E, SEZ6L2, and DOC2A, most of which are cancer-related." (PMID 37686578, 2023).
INO80E also shares sentences with these, for which no sentence is quoted: cardiac dysrhythmias (1 paper); Failure to thrive (1); major depressive disorder (1).